CST6 (cystatin E/M)
Diseases named in the same sentence as CST6 in open-access papers (continued):
Sharing a sentence is not in itself a finding about the gene and the disease.
melanoma (10 papers, 2008 to 2025). A malignant, usually aggressive tumor composed of atypical, neoplastic melanocytes. "Particularly, the correlation coefficients of epithelial cell and EMT score in SKCM were reversed, which indicated a potential role of CST6 in the metastasis of melanoma." (PMID 34603393, 2021). "Afterward, this tumor-suppressing role was corroborated with other cancers (cutaneous carcinoma, melanoma, lung, cervical, brain, neck, prostate, gastric and renal cancers) and the use of CST6 as a valuable biomarker was confirmed." (PMID 33919854, 2021). "We found that the expression pattern of CST6 was consistent in breast, pancreatic, lung, melanoma, and renal cancer between TCGA and MMDs datasets." (PMID 34603393, 2021). "In particular, we found that CST6 serves a protective function in the process of melanoma metastasis." (PMID 34603393, 2021). "On the other hand, CST6 is involved in the suppression of proliferation, migration and metastasis of melanoma." (PMID 33919854, 2021). "The tumor-suppressive function of CST6 has also been reported in lung cancer, melanoma, and renal cell carcinoma, which agreed with the loss expression of CST6 in these cancer types." (PMID 34603393, 2021). "Previously, we have reported an inverse correlation between secreted 17 kDa cystatin E/M and active legumain in melanoma cells." (PMID 23326369, 2013). "Several non-melanoma controls secreted cystatin E/M, including DU145, HCT-116 and MA11, and nearly equal amounts of unglycosylated (14 kD) and glycosylated (17 kD) forms were found." (PMID 20074384, 2010). "Among the four melanoma lines secreting cystatin E/M, the glycosylated form (17 kD) was predominant compared to the non-glycosylated form (14 kD)." (PMID 20074384, 2010). "Among the four melanoma lines secreting cystatin E/M, the glycosylated form (17 kD) was predominant compared to the non-glycosylated form (14 kD) in media from all but one cell line (MCC70)." (PMID 20074384, 2010). "The data presented provide new insight into the role of cystatin E/M in protease regulation and invasion in malignant melanoma." (PMID 20074384, 2010). "By immunoblotting, we detected cystatin E/M secretion from four melanoma cell lines (MCC13, 57, 70 and 72), and the conditioned media from these cells demonstrated the highest inhibitory activities against legumain." (PMID 20074384, 2010). "When melanomas with intermediate Breslow's tumor thickness were compared to thick primary lesions, a substantial (nearly 70-fold) decrease in CST6 gene expression was observed." (PMID 20074384, 2010). "Cystatin E/M was undetectable in media from all established melanoma cell lines examined, whereas strong immunobands were detected in two of five primary melanoma lines and in two of six lines derived from patients with metastatic disease." (PMID 20074384, 2010). "Surprisingly, we detected cystatin E/M by ELISA in media from only one of these melanoma cell lines." (PMID 20074384, 2010). "Further studies are needed to elucidate the role of both cystatin E/M and legumain in melanoma, including their expressions during different stages of the disease and their roles in tumor formation and metastasis in vivo." (PMID 20074384, 2010). "In this study, we provide data indicating that cystatin E/M suppresses invasiveness of melanoma cells, likely via the inhibition of the cysteine protease legumain known to be present in metastatic lesions." (PMID 20074384, 2010). "Collectively, our data strongly suggests that cystatin E/M inhibits melanoma progression by suppressing legumain activity." (PMID 20074384, 2010). "Legumain, cathepsin B and L were expressed and active in most of the cell lines, although at low levels in the melanomas expressing cystatin E/M." (PMID 20074384, 2010). "Although it is known that cystatin E/M is secreted by keratinocytes and is present in the skin, little is known concerning its expression in melanocytes or melanoma cells." (PMID 20074384, 2010).
melanoma (continued). "Over-expression of cystatin E/M, a legumain inhibitor, suppresses melanoma cell invasion." (PMID 29541256, 2018). "It is also possible that the amount of cystatin E/M in the media collected from the melanoma lines is below the limit of detection in the ELISA assay, as some cell lines showing strong expression on immunoblotting (e.g. HCT-116, MA11) had low amounts detected by ELISA." (PMID 20074384, 2010). "This led us to hypothesize that cystatin E/M expression may be lost during the initial phases of melanoma tumor progression." (PMID 20074384, 2010). "Interestingly, the glycosylated 17 kD cystatin E/M form predominated in the melanoma samples, whereas the unglycosylated 14 kD form predominated in HaCaT keratinocytes." (PMID 20074384, 2010). "Furthermore, invasion was suppressed in cystatin E/M over-expressing melanoma cell lines as measured by the transwell Matrigel assay." (PMID 20074384, 2010). "We have observed expression of cystatin E/M, legumain, cathepsin B and L in multiple melanoma cell lines, and an inverse correlation between secreted levels of the cysteine protease inhibitor and cellular activities of legumain and cathepsin B (but not cathepsin L) was detected." (PMID 20074384, 2010). "However, we could not detect any changes in cathepsin B activity when over-expressing cystatin E/M in melanoma cells." (PMID 20074384, 2010). "Among all the melanoma cell lines studied, cystatin E/M was only detected in the primary line MCC70 (0.28 ng/ml), whereas several of the non-melanoma lines displayed detectable levels (0.05-0.55 ng/ml)." (PMID 20074384, 2010). "For other genes, such as SPP-1, GDF15 (putative oncogenes), PITX-1 and CST6 (putative TSG), the major shifts in gene expression appear to occur at distinct but different times during the thickening of the primary melanoma tumors." (PMID 18442402, 2008). "Like cystatin D in the leukemia cells studied here, cystatin E/M was not expressed in the melanoma cells." (PMID 32810913, 2020). "Although cystatin E/M is normally expressed in the skin, its role in cysteine protease regulation and progression of malignant melanoma has not been studied." (PMID 20074384, 2010). "In the melanoma lines where cystatin E/M was secreted, cystatin C was generally absent or expressed at a very low level." (PMID 20074384, 2010). "Two melanoma cell lines lacking detectable secretion of cystatin E/M were transfected with a cystatin E/M expression plasmid (pCST6), and migration and invasiveness were studied by a Matrigel invasion assay." (PMID 20074384, 2010). "When melanoma cells lacking secretion of cystatin E/M were transfected with pCST6, their intracellular legumain activity was significantly inhibited." (PMID 20074384, 2010). "However, in the melanoma lines where cystatin E/M was secreted, cystatin C was generally absent (MCC13, MCC57 and MCC72) or expressed at a very low level (MCC70)." (PMID 20074384, 2010). "However, there has been no histological examination of cystatin E/M expression in nevi, melanoma in situ or primary melanoma." (PMID 20074384, 2010). "Although the expression of cystatin E/M in melanocytes has not been demonstrated, it has previously been shown that the protein is secreted from keratinocytes and thus present within the tumor microenvironment of the primary melanoma." (PMID 20074384, 2010).
breast tumor (5 papers, 2008 to 2021). "CST642 is a breast tumor suppressor expressed in normal breast epithelium, but epigenetically silenced as a consequence of promoter hypermethylation in metastatic breast cancer cell lines, which suggests the mechanism of CST6 loss during breast tumorigenesis and/or progression to metastasis." (PMID 27786176, 2016). "The prognostic significance of the methylation status of CST6 as a cancer biomarker in breast tumors was statistically evaluated." (PMID 33919854, 2021). "In this study we show for the first time that the putative breast tumor suppressor gene CST6 is consistently repressed by the oncogenic transcription factor TBX2 through a mechanism involving EGR1." (PMID 24742492, 2014).
pancreatic cancer (5 papers, 2010 to 2025). "CST6 may function as a prognostic biomarker for HCC, with a high CST6 expression being associated with poor survival of patients, in correlation with a previous report claiming that cystatin M/E could be a pancreatic tumor promotor." (PMID 33919854, 2021). "In studies on oral cancer, pancreatic cancer, thyroid cancer, and liver cancer, CST6 has been found to play a key role in tumor promotion." (PMID 40745648, 2025). "A study in pancreatic cancer showed that knockdown of cystatin E/M with siRNA suppressed in vitro growth whereas over-expression increased growth rate and tumor burden in vivo in pancreatic cancer." (PMID 20074384, 2010).
cyst (4 papers, 2019 to 2020). A sac-like closed membranous structure that may be empty or contain fluid or amorphous material. "This study revealed 5 new bradyzoite-upregulated GRAs which localized to the tissue cyst wall and cyst matrix (named CST2 –CST6)." (PMID 32374791, 2020). "This analysis yielded an inventory of previously undescribed cyst wall proteins (CST2/GRA50, CST3/GRA51, CST4, CST5/GRA52, and CST6/GRA53) that were validated to localize to the cyst wall by immunofluorescence." (PMID 32019789, 2020). "We also detected differential phosphorylation of the cyst wall proteins CST1, CST3, CST4, and CST6." (PMID 32907954, 2020). "For example, proteins CST3, CST5, CST6, CST7, GRA3, and GRA14 were detected in the cyst wall proteome but not within the interactome." (PMID 32019789, 2020).
gastric cancer (4 papers, 2021 to 2025). A primary or metastatic malignant neoplasm involving the stomach. "Moreover, CST6 was also part of a CpG island methylator phenotype-related prognostic gene signature which differentiated gastric cancer into high-and low-risk groups with a significant OS difference." (PMID 36389725, 2022). "A negative correlation was found between VSTM2L and CIMP, and a CIMP-related gene signature comprising six genes (VSTM2L, CST6, SLC7A2, RAB3B, IGFBP1, and EVX2) stratified gastric cancer patients into high‐ and low-risk groups with distinct prognoses." (PMID 35155565, 2021). "Analysis of the methylation status of CST6 in gastric carcinomas and their paired adjacent non-tumor tissues revealed a loss of expression of cystatin M/E in 70% of gastric carcinomas due to promoter hypermethylation." (PMID 33919854, 2021).
lung carcinoma (4 papers, 2010 to 2024). "Regarding the most downregulated cancer type in the two datasets, the coexpression genes of CST6 (Pearson correlation > 0.3) were commonly shared between MMDs lung cancer and TCGA LUAD/LUSC datasets, showing a statistically significant overlap (hypergeometric test, p-value < 2.2e-16)." (PMID 34603393, 2021). "Thus, CST6 and ITGA3 may be potential therapeutic targets for lung cancer." (PMID 34603393, 2021).
multiple myeloma (4 papers, 2022 to 2024). "BCMA-CST6-CAR-T cells target multiple myeloma and release large amounts of CST6 to suppress osteolytic lesions." (PMID 37883186, 2024). "We have demonstrated that both purified CST6 and BM serum from patients with high CST6 expression suppress osteoclast function and differentiation in a CST6-dependent fashion and that recombinant CST6 inhibits bone disease in an in vivo myeloma mouse model." (PMID 35881476, 2022). "Recombinant CST6 inhibited bone destruction in ex vivo and in vivo myeloma models." (PMID 35881476, 2022). "We have previously demonstrated that cystatin E/M (CST6), which is elevated in a subset of patients with multiple myeloma (MM) lacking osteolytic lesions (OLs), suppresses MM bone disease by blocking osteoclast differentiation and function." (PMID 37883186, 2024).
prostate carcinoma (4 papers, 2011 to 2021). A carcinoma that arises from epithelial cells of the prostate gland. "Moreover, the expression of CST6 was specifically dysregulated in liver, ovarian, and prostate cancer for the MMDs." (PMID 34603393, 2021). "Another study demonstrated that CST6 overexpression decreased metastasis in prostate cancer." (PMID 28225791, 2017).
triple-negative breast carcinoma (4 papers, 2020 to 2025). An invasive breast carcinoma which is negative for expression of estrogen receptor (ER), progesterone receptor (PR), and human epidermal growth factor receptor 2 (HER2). "In triple-negative breast cancer, CST6 expression is associated with a high risk of lymph node metastasis." (PMID 40745648, 2025). "An analysis of differential gene expression of triple-negative breast cancer (TNBC)-derived MDA-MB-231 cells demonstrated that CST6 was also strongly repressed, in addition to type 2 cystatin genes (CST1, CST2 and CST4), which are all encoded by a gene cluster on 20p11." (PMID 33919854, 2021). "CST6 has been reported to play a role in the progression of triple-negative breast cancer (TNBC) and may act as a tumor-promoter gene." (PMID 32821544, 2020).
glioma (3 papers, 2010 to 2021). A benign or malignant brain and spinal cord tumor that arises from glial cells (astrocytes, oligodendrocytes, ependymal cells). "One study has shown that the hypermethylation status of CST6 promoter resulted in CST6 deficiency in glioma tumor-initiating cells, while the promoter was hypomethylated in normal brain tissues." (PMID 34603393, 2021). "In glioma, expression of cystatin E/M inhibited cell motility and invasion in vitro." (PMID 20074384, 2010). "Moreover, CST6 expression by glioma tumor initiating cells (TIC) was fully hampered by promoter methylation, while the ectopic expression of cystatin M/E reduced TIC motility and invasion." (PMID 33919854, 2021).
lymph node metastasis (3 papers, 2020 to 2025). "Previous studies have shown that CST6 expression was associated with lymph node metastasis." (PMID 40745648, 2025). "High CST6 expression was also associated with a higher rate of lymph node metastasis." (PMID 32821544, 2020).
renal cell carcinoma (3 papers, 2012 to 2021). "Epigenetic study by high-density gene expression microarrays of renal cell carcinoma (RCC) cell lines identified eight genes, including CST6, exhibiting tumor-specific promoter region hypermethylation associated with transcriptional silencing." (PMID 33919854, 2021).
breast fibroadenomas (2 papers, 2012 to 2017). "However, one out of 9 fibroadenomas (11.1%) showed approximately 10% methylation for CST6 promoter." (PMID 23088560, 2012). "CST6 promoter was methylated in 3/29 (10.3%) non-cancerous breast tissues (mammoplasties) and in 1/10 (10.0%) breast fibroadenomas." (PMID 29069768, 2017).
cervical cancer (2 papers, 2021 to 2022). A primary or metastatic malignant neoplasm involving the cervix. "The results showed that PLCB4, FBLN5, TSPAN8, CST6, and SERPINB7 were highly expressed in cervical cancer tissues (p<0.05)." (PMID 36408178, 2022).
colon cancer (2 papers, 2013 to 2025). "In colon cancer, CST6 expression in tumor tissues is significantly higher than that in normal colon tissues and is significantly associated with the vascular endothelial growth factor PDGFR and EMT signaling pathway." (PMID 40745648, 2025). "Therefore, discrepancy in cystatin E/M expression can probably not explain the observed differences in mature 36 kDa legumain between the two colon cancer cell lines." (PMID 23326369, 2013).
leiomyoma (2 papers, 2007). A well-circumscribed benign smooth muscle neoplasm characterized by the presence of spindle cells with cigar-shaped nuclei, interlacing fascicles, and a whorled pattern. "A balance between cell growth and apoptosis is critical in progression of tissue fibrosis and the expression of several genes functionally related to these categories, including Bcl-XL, Bad, Bax, p27Kip1, p57Kip2, Gas1, Gas7, CST6, CST7, caspases, etc., were identified in leiomyomas and myometrium." (PMID 17716379, 2007).
osteoporosis (2 papers, 2023 to 2025). A condition of reduced bone mass, with decreased cortical thickness and a decrease in the number and size of the trabeculae of cancellous bone (but normal chemical composition), resulting in increased fracture incidence. "To confirm the ability of CST6 to inhibit osteoclastic bone resorption, we next determined if CST6 could inhibit bone loss in a murine model of estrogen deprivation-induced osteoporosis similar to ZA." (PMID 40075680, 2025). "Of four key crosstalk genes (ARHGEF10, PCDH7, CST6, and ROBO3), PCDH7 was identified and validated as relating the development of both sarcopenia and osteoporosis." (PMID 37476411, 2023).
pancreatic ductal adenocarcinoma (2 papers, 2020 to 2021). An infiltrating adenocarcinoma that arises from the epithelial cells of the pancreas. "Cystatin 6 (CST6) is overexpressed in pancreatic ductal adenocarcinoma (PDAC) cells and can stimulate PDAC cell growth by reducing the activity of intracellular cathepsin B." (PMID 33173782, 2020).
papillary thyroid carcinoma (2 papers, 2015 to 2021). "As it has been noted on previous work: CST6, CXCL14, DHRS3, and SPP1 are regulated by BRAF signaling and may play a role in papillary thyroid carcinoma pathogenesis." (PMID 25887408, 2015).